AKAP17A (A-kinase anchoring protein 17A)
Description:
Splice factor regulating alternative splice site selection for certain mRNA precursors. Mediates regulation of pre-mRNA splicing in a PKA-dependent manner.
Synonyms: AKAP-17A; PRKA17A; CXYorf3; DXYS155E; SFRS17A; XE7; XE7Y; MGC39904; 721P; CCDC133
Tractability: PROTAC: UniProt records ubiquitination sites on it; ubiquitination databases record sites on it; its protein half-life has been measured.
Gene: Protein-coding gene on chromosome X (1,591,604 to 1,602,532, forward strand). Ensembl gene ENSG00000197976.
Subcellular location: Nucleus speckle
Subcellular location (Human Protein Atlas): Nuclear speckles; Cytosol
Gene Ontology:
Molecular function: protein binding; protein kinase A binding; RNA binding; nucleic acid binding
Biological process: regulation of RNA splicing; B cell activation; regulation of DNA-templated transcription; signal transduction
Cellular component: nuclear speck; nucleus
Homologues: Orthologues: chimpanzee AKAP17A (99% identical), macaque AKAP17A (96% identical), dog AKAP17A (89% identical), pig AKAP17A (83% identical), tropical clawed frog akap17a (62% identical), mouse Akap17a (55% identical), zebrafish akap17a (48% identical), rat Akap17a (43% identical), Drosophila melanogaster Xe7 (34% identical), Caenorhabditis elegans cux-7 (26% identical).
Diseases named in the same sentence as AKAP17A in open-access papers:
AKAP17A is named in the same sentence as 12 diseases in open-access papers, as found by Europe PMC text mining. Sharing a sentence is not in itself a finding about the gene and the disease. The quoted sentences say what the papers report.
cognitive decline (2 papers, 2019 to 2024). "We present here evidence to suggest that expression levels of HNRNPM, HNRNPA0 and AKAP17A genes may be associated with cognitive decline, whilst AKAP17A levels may be associated with decline in physical performance in a human population." (PMID 31292793, 2019).
Autoimmunity (1 paper, 2023). The occurrence of an immune reaction against the organism's own cells or tissues. "The only PAR gene that emerged was a variant in AKAP17A (X:1601004:C-G) associated with autoimmunity." (PMID 37800145, 2023).
chronic tic disorder (1 paper, 2018). A neurological disorder presenting in childhood that is characterized by either motor or phonic tics, but not both, that occur daily or nearly daily for at least a year and are not attributed to an identifiable cause. "Both ZBED1 and PPP2R3B may have a role in the regulation of cell growth and division, and AKAP17A has been associated with chronic tic disorder." (PMID 30213969, 2018).
AKAP17A also shares sentences with these, for which no sentence is quoted: acute lymphoblastic leukemia (1 paper); B-cell acute lymphocytic leukemia (1); cancer (1); diffuse large B-cell lymphoma (1); infection (1); leukemia (1); melanoma (1); non-Hodgkin lymphoma (1); skin cancer (1).